RNU6-383P (RNA, U6 small nuclear 383, pseudogene)
Gene: Small nuclear RNA gene on chromosome X (150,955,494 to 150,955,587, reverse strand). Ensembl gene ENSG00000222796.
Homologues: Orthologues: chimpanzee U6 (97% identical), macaque U6 (84% identical). Paralogues in human: RNU6-1011P (87% identical), RNU6-21P (87% identical), RNU6-774P (87% identical), RNU6-1158P (86% identical), RNU6-33P (86% identical), RNU6-38P (86% identical), RNU6-43P (86% identical), RNU6-468P (86% identical), RNU6-1 (85% identical), RNU6-1042P (85% identical), RNU6-1189P (85% identical), RNU6-1309P (85% identical), and 1287 more.